EGFR (epidermal growth factor receptor)
Diseases named in the same sentence as EGFR in open-access papers (continued):
Sharing a sentence is not in itself a finding about the gene and the disease.
tumor (continued). "Therefore, the occurrence of functional integrity of the RAS-driven pathways - BRAF-MEK-ERK and PIK3CA-AKT - is necessary in order to really interfere with tumour cell growth through inhibition of EGFR target." (PMID 22931052, 2012). "From these data, we hypothesise that the tumour microenvironment elicits TGFβ1 and stimulates a miRNA gene expression program that induces resistance to anti-EGFR therapy and drives lung tumour cells to EMT, invasion, and metastasis." (PMID 22045191, 2012). "Addition of epidermal growth factor receptor (EGFR)-targeted agents (e.g. the chimeric antibody cetuximab or the fully human antibody panitumumab) to FOLFIRI also significantly improves outcomes in patients with wild-type (WT) KRAS tumours." (PMID 23020584, 2012). "Four mechanisms have been proposed to explain tumor resistance to EGFR TKIs." (PMID 22545054, 2012). "The mechanism of action of EGFR targeting monoclonal antibodies is proposed to be a blockade of tumor survival signals that affect proliferation, apoptosis, and DNA repair as well as the stimulation of the immune system to recognize and target tumor cells for destruction." (PMID 23150825, 2012). "In addition, EGFR activation also indirectly affects factors that play an important role in tumor cell survival and growth such as vascular endothelial growth factor directed angiogenesis." (PMID 22918789, 2012). "It has been proposed that EGFR may participate in the carcinogenesis process of EA, based on the fact that EGFR may stimulate proliferation and migration of tumor cells." (PMID 22792097, 2012). "Therefore, we were interested in exploring the expression of EGFR in circulating tumor cells (CTCs) of patients with BC." (PMID 22554015, 2012). "Expression of pTyr1068 in tumor samples evaluated by IHC here exhibits a strong predictive value for EGFR-TKIs therapy, especially in patients without EGFR mutations." (PMID 22901364, 2012). "Accordingly to direct sequencing analysis, these tumours included 70 EGFR wild-type and 19 EGFR mutants: 11 with exon 19 deletions, of which nine with E746-A750del and two with complex deletions, L747-A750>P and L747-P753>S; five with L858R; and three with exon 20 insertions." (PMID 22952784, 2012). "All of the three positive cases presented EGFR staining in the entire tumor." (PMID 23207070, 2012). "In addition, overexpression of EGFR has been shown to correlate with lower tumor control rates after irradiation in several studies." (PMID 23232108, 2012). "Interestingly, therapies targeting both EGFR and Her 2 have been shown to normalize tumor vascularization." (PMID 22988345, 2012). "EGFR mRNA levels correlated with protein levels in the tumor tissue." (PMID 23153332, 2012). "Moreover, EGFR-inhibitors inhibit not only the EGFR when overexpressed in tumor cells, but also the receptor present on normal cells of the epidermis." (PMID 22640460, 2012). "Since regeneration and tumour cell proliferation are mechanisms at the cellular level, particular attention has been focused on identifying the specific cellular characteristics, such as variations in EGFr expression." (PMID 22920680, 2012). "However, there are reports suggesting potential discordance between the primary tumour and metastases regarding EGFR status." (PMID 22666589, 2012). "In conclusion, the current study assessed whether EGFR expression predicts tumor staging and survival in EA patients treated with transhiatal esophagectomy." (PMID 22792097, 2012). "In vitro, it has been described that soluble isoforms may regulate EGFR signaling in normal and tumor cells." (PMID 22159595, 2012). "In contrast, EGFR cytoplasmic staining is significantly higher in normal than in tumor tissues." (PMID 23202921, 2012). "Moreover, some studies also demonstrated that tumours with high EGFr respond better to the reduction of the OTT compared to low EGFr tumours." (PMID 22920680, 2012).
tumor (continued). "Irrespective of the type of cancer being treated and the mechanism by which tumor EGFR drives tumorigenesis, the major side effect of EGFR inhibition is a papulopustular (also described as maculopapular or acneiform) rash which occurs in about two thirds of the patients." (PMID 22997576, 2012). "Thus, treatments that combine EGFR inhibitors with conventional chemotherapy will target both the bulk of the tumor and the cancer stem cell subpopulation, greatly reducing the possibility of relapse and secondary tumors." (PMID 22384257, 2012). "Therefore ErbB2 tumor cells obtained from this transgenic model are dependent on activated EGFR for growth and survival and can be rescued by Met activation." (PMID 23028720, 2012). "Additionally, tumours with EGFR hypermethylation are more resistant to tyrosine kinase inhibitor, which indicates a poorer prognosis." (PMID 22264301, 2012). "This hypothesis is based on the clinical observation that high levels of EGFr expression were found to be more pronounced at the tumour borders compared to the central parts of the tumour tissue (p < 0.0001)." (PMID 22920680, 2012). "In total, 53 tumours (19.7%) presented overexpression of EGFR." (PMID 22240798, 2012). "Noninvasive molecular imaging techniques for quantitatively assessing tumor biochemical status based on quantitative EGFR imaging would facilitate initial in vivo selection of therapeutic carepaths and provide a tool for longitudinal monitoring of early recurrence." (PMID 23029451, 2012). "The role of ADCC induced by EGFR-specific mAbs may prevent tumor outgrowth or metastasis in vivo, even in cancers insensitive to EGFR signaling inhibition." (PMID 23171437, 2012). "In addition to whole EGFR, tumor cells express sEGFR proteins that can be generated by alternative mRNA splicing events, via proteolytic cleavage of the receptor or by aberrant translocation events." (PMID 22623992, 2012). "These aptamers also inhibit tumor growth in mice and induce apoptosis of tumor cells resistant to current antibody and chemical based anti-EGFR treatment, likely due to the aptamers small size and the inhibition of multiple forms of EGFR present on cell surfaces." (PMID 23130020, 2012). "Evaluation of CD10 and Ki67 status together with conventional histological evaluation can help in providing more information about the biologic behavior of the tumor, while EGFR could be a target of an expanding class of anticancer therapies." (PMID 22300665, 2012). "Taken together our results identify AR as a new downstream target of FGF19 in HCC cells, and reveal a functional cross-talk in which the AR/EGFR system could mediate, and likely amplifiy, the tumor-promoting effects of FGF19." (PMID 23285165, 2012). "It targets key signalling pathways in cancer by inhibiting vascular endothelial growth factor receptor (VEGFR)-dependent tumour angiogenesis, and epidermal growth factor receptor (EGFR), and rearranged during transfection (RET)-dependent tumour cell proliferation and survival." (PMID 22363427, 2012). "EGFR-mediated signal transduction pathways are very extensive and important, and they involved in growth, differentiation, proliferation and anabolism regulation of tumor cells." (PMID 23046633, 2012). "Stabilized HIF-2α, often found in the hypoxic core of the tumor, upregulated the expression of EGFR which may contribute to tumor growth, and the activation of EGFR signaling pathway was associated with the development of K-19-positive HCC." (PMID 22768190, 2012). "Besides its relatively high prevalence, EGFR expression was related with more advanced lesions, with higher scores either for tumor staging, nodal involvement, or metastasis." (PMID 22792097, 2012). "In addition to its possible role in tumor progression, higher tumor EGFR expression has been correlated with worse prognosis in patients with MPNST." (PMID 23319880, 2012).
tumor (continued). "Therefore, the existing multi-scale agent-based tumor models incorporated an EGFR signaling pathway at the molecular scale to enable individual cells to choose their phenotypic trait between proliferation and migration based on the pathway's state." (PMID 22935054, 2012). "All specimens demonstrated EGFR-positively stained tumor cells." (PMID 22300665, 2012). "For example, the mean EGFR GCN of different sections within a tumor could be highly heterogeneous, leading to potential misclassification of EGFR GCN status in up to 39% of patients." (PMID 22897982, 2012). "The reliability of this analytical approach was demonstrated by application of this assay to FFPE human xenograft tumor tissue, in which the ability to measure EGFR protein levels was demonstrated to be consistent with previously-determined EGFR levels in these samples." (PMID 22554165, 2012). "Therefore, combination therapy which uses erlotinib can be considered effective if epidermal growth factor receptor phosphorylation is inhibited by erlotinib, even in erlotinib-resistant tumor xenograft models." (PMID 22209766, 2012). "Some studies indicate that soluble isoforms could regulate EGFR signaling in normal and in tumor tissues." (PMID 22623992, 2012). "In addition, OPN also increases the activity of EGFR tyrosine kinase, and Met kinase to promote tumor cell migration by inducing EGFR and HGFR (Met) expression." (PMID 22537906, 2012). "Furthermore, it has been shown that tumours with high expression of EGFr have a better LCR when treated with accelerated radiotherapy, while there was no benefit of acceleration in tumours with low EGFr." (PMID 22920680, 2012). "Mutations in the EGFR play a decisive role in the response by the tumor to EGFR-targeted therapy." (PMID 22815959, 2012). "Having shown that SecinH3 reduces the proliferation of EGFR-wild type NSCLC cells in vitro we asked whether tumor growth would be inhibited also in vivo." (PMID 22815959, 2012). "In addition, the nature of the cells (endothelial or tumor cells), expressing EGFR protein has also been discussed." (PMID 22623992, 2012). "Importantly, recent studies have demonstrated that activated EGFR recruits and activates SFKs leading to enhanced tumor cell invasion and metastasis." (PMID 22586492, 2012). "The dose of gefitinib might have been subtherapeutic in patients with wild-type EGFR tumours, and this notion is supported by the lower than expected proportion who developed rash." (PMID 23078958, 2012). "In conclusion, c-erb-B2, EGFR, mTOR, and ERCC1 overexpression and p27 loss may play roles in hepatocarcinogenesis and may be significant predictors of aggressive tumor behavior." (PMID 23162604, 2012). "It is possible that the difference observed in OS may be a result of patients with WT KRAS tumours receiving anti-EGFR therapy after the treatment of the study." (PMID 23174912, 2012). "Irrespective of the type of cancer being treated and the mechanism by which tumor EGFR drives tumorigenesis, the major side effect of EGFR inhibition is a papulopustular (also described as maculopapular or acneiform) rash which occurs in about two thirds of treated patients." (PMID 22997576, 2012). "A kinase inhibitor targeting PDGFRA and/or FGFR or other frequently activated tyrosine kinases that can reach effective intra-tumor concentrations before dose limiting toxicity is a likely candidate for a combination with an EGFR inhibitor for a potentially more effective therapy." (PMID 23056179, 2012). "Thus, new strategies to overcome tyrosine kinase inhibitors (TKI) resistance are under active exploration and there is the urgent need to design new EGFR-targeting drugs for a more specific and selective tumor therapy." (PMID 21915281, 2011). "Vandetanib could inhibit tumour cell proliferation and survival by blocking EGFR and could inhibit tumour-induced neo-angiogenesis by blocking VEGF activity and has been investigated in a variety of human cancers, including NSCLC." (PMID 21750552, 2011).
tumor (continued). "Gefitinib and erlotinib are tailored drugs that compete with adenosine triphosphate (ATP) for the ATP binding site on the EGFR and thereby prevent phosphorylation and activation of downstream signalling molecules involved in cell proliferation and tumour growth." (PMID 22095231, 2011). "Also, in our previous study, it was found that EGFR-lytic hybrid peptide targeting epidermal growth factor receptor (EGFR) administrated intravenously reduced the growth of EGFR-expressing tumor with a dose as low as 2 mg/kg." (PMID 21849092, 2011). "Additionally, the frequency of EGFR-specific CTL in the peripheral blood of HNSCC patients correlated strongly with the EGFR expression on tumor samples." (PMID 21970318, 2011). "Since NFκB is able to regulate more than 150 genes, and is able to functionally orchestrate many steps in carcinogenesis, tumor progression and metastasis, it is important to delineate the efficacy of potential EGFR-TK inhibitors that target the NFκB-dependent HNSCC cell survival advantage." (PMID 22242139, 2011). "Furthermore, we demonstrated that discordance of test results between primary tumour and metastases cannot account for the failure rate of anti-EGFR therapy in patients with KRAS wild-type tumours." (PMID 21364579, 2011). "In this situation, there appears to be dual input to signaling and combined inhibition of EGFR and the alternative pathway may be necessary to kill tumor cells." (PMID 21444946, 2011). "It is thought that elevated expression of epiregulin and/or amphiregulin may stimulate an autocrine loop through EGFR thus promoting tumor growth and survival." (PMID 24212785, 2011). "Therefore, the European Medicines Agency and the Food and Drug Administration have restricted the use of anti-EGFR antibodies in metastatic CRC to patients with KRAS wild-type tumours." (PMID 21364579, 2011). "When using body fluids for EGFR mutation analysis, positive result is consistently a good indicator for TKIs therapy, and the predictive effect was no less than that of tumor tissue, no matter what method was employed." (PMID 22142557, 2011). "There appear to be distinct mechanisms for EGFR activation in different types of human neoplasms." (PMID 21730982, 2011). "The development of microsatellite tumours could be inhibited by combined treatment with mAbs against epidermal growth factor receptor, known to stimulate GBM migration and invasion." (PMID 21829586, 2011). "In that context, we hypothesised that the PDAC stromal component may influence ErbB-mediated signalling with resultant critical effects on tumour cell proliferation and response to EGFR-targeted agents." (PMID 21792199, 2011). "Therefore, EGFR-targeting would have a double impact—arresting tumor cell proliferation and impairing tumor immune evasion." (PMID 24212794, 2011). "However, the limited number of preclinical models that recapitulate the invasive GBM tumor growth with the overexpression of EGFR is a major hurdle to develop new therapies for GBM." (PMID 21314332, 2011). "The fact that phosphor-EGFR positive cells are present in the tumor that has responded to cetuximab, also implies that cells which have acquired cetuximab may have selectively survived in response to the treatment." (PMID 21554739, 2011). "In addition to direct anti-EGFR effect, IgG1 mAbs such as cetuximab mediate anti-tumor effects by the ADCC mechanism." (PMID 22117530, 2011). "We understand that this proposed mechanism could be just one of the many plausible scenarios explaining resistance to EGFR-targeted therapies since alternative escape routes such as TGF-β and IL-6 axis have been implicated in other tumour types." (PMID 21792199, 2011). "A significant correlation was found between mRNA and protein levels, whereas no statistical associations were found between EGFR and TS, as well as between EGFR and TS levels and tumour histology/stage/grade." (PMID 21970874, 2011).
tumor (continued). "Therefore, it has been expected that the treatment with EGFR inhibitors, including anti-EGFR antibodies, would be highly successful in inducing tumor regression." (PMID 21970318, 2011). "We previously showed that 11C-erlotinib could be used to identify tumours overexpressing the EGFR in animal models, and we have presented a case report showing accumulation of 11C-erlotinib in brain metastasis of a patient with NSCLC." (PMID 22095231, 2011). "Moreover, number of pathologically positive lymph nodes and EGFR numerical aberrations of the primary tumours were also shown to be excellent predictors of ECS in OSCCs." (PMID 21304522, 2011). "Increased EGFR/HER2 expression may be a survival response by some tumours exposed to chemotherapeutic agents." (PMID 21997136, 2011). "The short duration of lapatinib before commencing CRT may have provided insufficient suppression of EGFR signalling to induce apoptosis, but may prime tumour cells for subsequent CRT-induced cell death through an unknown mechanism." (PMID 21829197, 2011). "Additional findings from our laboratory also point to the lack of activating mutations in EGFR and ErbB3 genes, giving further strength to ligand-driven tumour cell proliferation as a paramount tumourigenic mechanism within the PDAC microenvironment." (PMID 21792199, 2011). "Moreover, logistic regression analysis showed that the number of pathologically positive nodes and copy number aberrations of EGFR at the primary tumour are independent predictors of ECS." (PMID 21304522, 2011). "The predictive role of EGFR mutation was also demonstrated by the noteworthy differences in PFS observed in patients with EGFR mutation-positive or -negative tumours when treated with gefitinib (9.5 vs 1.5 months)." (PMID 21654681, 2011). "We conclude that EBUS-TBNA of lymph nodes infiltrated by NSCLC can provide sufficient tumour material for EGFR and KRAS mutation analysis in most patients, and that COLD-PCR and sequencing is a robust screening assay for EGFR and KRAS mutation analysis in this clinical context." (PMID 21949883, 2011). "The EGFR immunoreactivity was detected in the tumour cell cytoplasm." (PMID 21730982, 2011). "Although EGFR mutations occur early in the tumorigenesis process and one would, therefore, expect them to be homogeneous, tumor heterogeneity of EGFR mutations has not been assessed thoroughly so far." (PMID 21785682, 2011). "It is known that HIF can activate EGFR to promote tumor growth." (PMID 21949687, 2011). "Importantly, we found a strong correlation of specific T cell frequency and EGFR expression on tumor cells." (PMID 21970318, 2011). "There was a highly significant difference between patients' protein levels when comparing normal adjacent mucosa with the levels expressed in tumor cells for both Aurora-A and EGFR, with independent expression of EGFR and Aurora-A for each patient (r = 0.03 / p = 0.74)." (PMID 21865609, 2011). "It is also possible that chemotherapy during the EGFR-TKI-free interval could decrease EGFR-TKI resistant tumor cells." (PMID 21194487, 2011). "Small numbers of EGFR mutant tumours limited detailed analysis." (PMID 21385341, 2011). "Determination of the EGFR expression and the presence of mutations require a tumour biopsy, which is not possible to collect in all situations." (PMID 22095231, 2011). "Overall, our systems biology modeling together with experimental validations reveals that inhibition of survival signals and concomitant release of apoptotic potential jointly contribute to the tumor cell death following the inhibition of addicted oncogene in EGFR addicted cancers." (PMID 22194952, 2011). "If the tumor does not contain activating mutations on EGFR, treatment with TKIs will most likely be ineffective." (PMID 22142557, 2011). "Finally, out of 135 tumor samples, 8 (5.9%) showed amplification of EGFR gene, 10 (7.4%) demonstrated polysomy, and 117 (86.7%) had no changes of the EGFR gene." (PMID 22050898, 2011).